FOXP3 (forkhead box P3)
Diseases named in the same sentence as FOXP3 in open-access papers (continued):
Sharing a sentence is not in itself a finding about the gene and the disease.
autoimmune disease (continued). "Therefore, we hypothesize that gene transduction of naive CD4+ T cells with FoxP3 and Bcl-xL can induce the generation of highly reactive Tregs, which may be used in the treatment of autoimmune disease." (PMID 20384988, 2010). "Therefore, we tested the hypothesis that co-transduction of CD4+ T cells with both FoxP3 and Bcl-xL will generate highly reactive Tregs that can be used to prevent autoimmune disease." (PMID 20384988, 2010). "Similarly, human patients with mutations in the FoxP3 gene develop a multiple organ autoimmune disorder known as IPEX which is consistent with a lack of Treg cells." (PMID 16579866, 2006). "We have recently shown that systemic delivery of autoimmune disease-relevant pMHCII-NPs expands cognate TFH cells and triggers the transdifferentiation of these TFH cells into disease-suppressing Foxp3– TR1-like cells." (PMID 40066448, 2025). "In addition, hypoxia may support plasticity of Treg cells in detriment of their regulatory function on one side accelerating the degradation of the FoxP3 in the proteasome and enhancing proportions of Treg with a Th17 –like phenotype described also in several autoimmune diseases." (PMID 40963621, 2025). "In other autoimmune diseases with more complex etiologies, such as SLE and rheumatoid arthritis, the relationship between FOXP3+ Treg cells and disease pathogenesis is less clear." (PMID 39697333, 2024). "Active or passive demethylation by TET enzymes maintains hypomethylation of Foxp3’s TSDR, which plays a critical role in suppressing Tregs function for optimal treatment of autoimmune diseases." (PMID 39144146, 2024). "Currently, low-dose IL-2 therapy tried to treat various autoimmune diseases including RA, primary Sjögren's syndrome and SLE, has been shown to increase the number of CD4+CD25+FOXP3+Treg cells and achieved therapeutic results." (PMID 38240927, 2024). "Intriguingly, despite a significant increase in histone acetylation at the Foxp3 promoter and CNS2 in HDAC3-/- mice as confirmed by Chromatin Immunoprecipitation assay, it resulted in detrimental autoimmune diseases." (PMID 39144146, 2024). "Numbers of CD4+FOXP3+ Tregs are typically reduced in human and murine SLE, as well as in other autoimmune diseases, and our findings suggest a potential new role for dietary Mg supplementation in the treatment of SLE." (PMID 39242985, 2024). "Dleu2-17aa promotes Smad3 binding to the CNS1 region of Foxp3, regulates TGF-β/Smad signaling, and plays an anti-inflammatory role in autoimmune disease (Synopsis Fig)." (PMID 38291338, 2024). "Notably, these FOXP3 promoter SNPs can directly lead to changes in the binding of transcription factors, affecting the transcriptional activity of FOXP3 and its protein expression, which in turn may have an impact on the onset of autoimmune diseases." (PMID 38584670, 2024). "Inflammatory conditions, like in autoimmune diseases may result in conversion of FOXP3 + Tregs into Th17 cells, contributing to disease progression and impairing immune homeostasis, therefore stable full length expression of FOXP3 is a prerequisite for Treg cell therapy." (PMID 36562079, 2023). "Quantifying intracellular levels of acetyl-CoA and acetylation of Foxp3 and other specific transcription regulators involved in Treg development and function could provide more insights into the underlying mechanism of ACC1 inhibition and its clinical application in autoimmune disease." (PMID 37594540, 2023). "An increase in Treg FOXP3 and CTLA4 expression would stabilise the Treg cell phenotype and benefit patients with autoimmune disease." (PMID 34408239, 2021). "The adoptive transfer of CD4+CD25+ T cells prevented autoimmune disease development induced by CD4+CD25− T cells, and the suppressive function was defined later as dependent on the expression of transcription factor forkhead box P3 (Foxp3)." (PMID 32397343, 2020).
autoimmune disease (continued). "Hence, identifying the molecular mechanisms by which FOXP3 and miR-31 regulate each other and identifying the other downstream target genes in this regulatory network could assist in the development of novel treatments for autoimmune diseases." (PMID 33072063, 2020). "Given its role in Foxp3+ Treg biology, providing IL2 to Foxp3+ Tregs as an intervention for autoimmune diseases had been tested in clinic over the years." (PMID 32269069, 2020). "The stability of FoxP3 and the high levels of expression of CD25 molecules are important elements in the maintenance of Treg function and protection from autoimmune disease." (PMID 31275306, 2019). "However, Foxp3+ Tregs might become unstable; so, therapies combining the transfer of Tregs with Tregs-stabilizing drugs are expected to be the most effective ones to restrain autoimmune diseases." (PMID 31824482, 2019). "Before and in line with literature, we had clearly detected CNS-resident Tregs in mice diseased with experimental autoimmune disease, and at least a few CD4+ FOXP3+ cells were found in early active brain lesions of human MS patients." (PMID 32010141, 2019). "Foxp3+ Treg cells have been demonstrated effective in the control of autoimmune disease, and in DCM patients, a significant reduction in peripheral TGF-β and IL-10 with decreased Foxp3 expression contributed to an imbalance in the Treg/Th17 ratio." (PMID 30443223, 2018). "In mice, therapeutic approaches using Foxp3 gene-transduced CD4+ Tregs have been successful in the induction of tolerance in graft-versus-host disease and some autoimmune diseases." (PMID 29535721, 2018). "FoxP3 (forkhead transcription FoxP3-expressing natural Treg, including CD25+ and CD25− cells, plays an important role in inhibiting various autoimmune diseases, and depletion of these cells, which will result in autoimmune diseases." (PMID 29977885, 2018). "Thymus-derived natural Foxp3+ CD4+ regulatory T cells (nTregs) play a key role in maintaining immune tolerance and preventing autoimmune disease." (PMID 28690613, 2017). "Several other reports are consistent with our studies, indicating that Foxp3+ Treg numbers increase after B cell depletion by anti-CD20 and Treg were largely responsible for suppression of the autoimmune disease." (PMID 28134752, 2017). "CD4+CD25+FoxP3+ regulatory T (Treg) cells and CD8+CD28- Treg cells have roles in autoimmune diseases." (PMID 27211045, 2016). "As the knockout of FoxP3, mice that lack LAG-3 exhibit leucocyte infiltrate in multiple organs followed by autoimmune disease." (PMID 26115356, 2015). "To determine whether the modification of FoxP3 would increase susceptibility to spontaneous autoimmune disease, despite the lack of obvious detrimental alterations to their Treg cells we followed groups of Tg4 FoxP3wt and Tg4 FoxP3gfp males until 16–24 weeks of age." (PMID 23593464, 2013). "Consistent with the potential therapeutic role of regulatory T (Treg) cells against various autoimmune diseases, KD treatment in EAE mice resulted in a tendency toward increased CD4+CD25+Foxp3+ Treg cells." (PMID 22567104, 2012). "Collectively, these data suggest a scenario in which repetitive PTx treatment protects mice from development of CNS autoimmune disease through upregulation of regulatory cytokines and expansion of CD4+CD25+FoxP3+ Treg." (PMID 21209857, 2010). "Furthermore, genetic modification with FoxP3 and Bcl-xL using vectors containing the 2A sequence is able to generate highly reactive Tregs that could be used for augmented cellular immunotherapy for autoimmune disease." (PMID 20384988, 2010). "The importance of miRNAs in FoxP3+ CD4+ Treg development and immunosuppressive activity has been confirmed by FoxP3 driven deletion of DICER which results in mice that die of spontaneous inflammation and autoimmune disease." (PMID 19525145, 2009).
autoimmune disease (continued). "Defective development or depletion of Treg in animals, such as the naturally arising Foxp3+CD4+CD25+ Treg (nTreg), results in the development of autoimmune diseases, including type 1 diabetes (T1D)." (PMID 19924236, 2009). "Interestingly, a recent study has found a correlation between levels of Foxp3 expression and regulatory function, suggesting that failure to maintain optimal Foxp3 expression could compromise regulatory cell function and lead to autoimmune disease development." (PMID 19011680, 2008). "Thus, the TFH-TR1 transdifferentiation pathway results in the generation of two distinct autoimmune disease-suppressing, IL-10-producing TR1 subsets that are distinguished by the expression of Foxp3 and Foxp3 target genes." (PMID 40066448, 2025). "The thymus generates T cells from immature thymocytes and prevents autoimmune diseases through negative selection and the generation of FOXP3+ regulatory T cells (Tregs)." (PMID 41164186, 2025). "In contrast, continuous Foxp3 degradation for 4 weeks did not result in any noticeable clinical manifestations of autoimmune disease with only mildly increased state of immune cell activation observed." (PMID 41062655, 2025). "However, in various autoimmune diseases, the frequency and/or suppressive functions of peripheral CD4+CD25+FOXP3+ Tregs are abnormal." (PMID 40710338, 2025). "In sharp contrast, continuous Foxp3 degradation for four weeks did not result in any noticeable clinical manifestations of autoimmune disease with only mildly increased state of immune cell activation observed (Figure." (PMID 40470210, 2025). "Thus, understanding the mechanisms that regulate alternative FOXP3 splicing and exploiting the chemical factors that control this process may enable Treg activity to be modulated in vitro and in situ, providing an alternative therapy for a number of autoimmune diseases, including T1D." (PMID 41294856, 2025). "The persistence of this regulatory transcriptome highlights the importance for developing Treg-cell therapy strategies in cancer and autoimmune diseases independent of Foxp3 expression." (PMID 40568113, 2025). "Redundancy also explains why deletion of the NRP1 gene alone on Foxp3+ Tregs does not result in autoimmune disease." (PMID 40590224, 2025). "Foxp3+CD25+CD4+ natural regulatory T cells in dominant self-tolerance and autoimmune disease." (PMID 37469162, 2024). "Conversely, Forkhead Box P3 (FoxP3)+ Treg cells do not aid in the defense against pathogens but instead act to prevent autoimmune disorders by inhibiting undesired immune responses." (PMID 39273452, 2024). "The absence of Foxp3+ Tregs was involved in some autoimmune disease, like immune polyendocrinopathy, enteropathy, pemphigus." (PMID 36226375, 2023). "Tregs, which specifically expressed the forkhead transcription factor Foxp3, are known to attenuate immune activity, and the beneficial effects of MSC-sEVs-mediated enhanced generation of Tregs have been well documented in several autoimmune disorders." (PMID 35874782, 2022). "For this, we took advantage of the well-established DTR/GFP transgene of DEREG mice, which allows for specific ablation of Foxp3+ Treg cells without promoting catastrophic autoimmune diseases." (PMID 34447385, 2021). "Tregs are important for self-tolerance and suppressing autoimmune and inflammatory reactions as evidenced by multi-organ autoimmune disease observed in humans and mice lacking functional forkhead box protein P3 (FOXP3)." (PMID 34777255, 2021). "Moreover, the forkhead box P3 (FOXP3) gene was identified as a regulatory gene in CD25+CD4+ Tregs, which was crucial in autoimmune disease." (PMID 34806028, 2021). "Furthermore, the direct binding of KLF2 to the Foxp3 promoter was observed and Treg-specific deletion of KLF2 using a Foxp3-cre deleter resulted in the onset of autoimmune diseases (Table A1 in Appendix A)." (PMID 34696279, 2021).
autoimmune disease (continued). "These subsets express the master transcription factor, FOXP3, and include Tr1 cells and CD4+CD25+ Tregs, which are the main population involved in maintaining the peripheral tolerance, preventing the autoimmune diseases and limiting the chronic inflammatory diseases such as CD." (PMID 31952431, 2020). "Humans lacking functional Foxp3 develop early in infancy a severe and progressive autoimmune disease called IPEX, immunodysregulation, polyendocrinopathy, and enteropathy X-linked syndrome." (PMID 30067137, 2019). "The second mechanism through which TCDD may suppress Th17 cells may result from its ability to increase the expression of FoxP3 and to induce more Tregs, as seen in the current study using PTX and as seen in other autoimmune disease models." (PMID 31681214, 2019). "In several other autoimmune diseases, such as lupus nephritis, idiopathic thrombocytopenic purpura, myasthenia gravis, and rheumatoid arthritis, treatment with rituximab significantly increased the growth of CD4+ CD25bright FoxP3+ Treg cells." (PMID 31428090, 2019). "FOXP3+ Tregs are also modulated by AHR and play a role in autoimmune disease." (PMID 30574142, 2018). "Thymic-derived and peripherally induced CD4+CD25+FoxP3+ Tregs are critical immune regulators to prevent autoimmune disease and for tolerance to “non-self” antigens." (PMID 29225598, 2017). "The lack of a functional Foxp3 transcription factor and regulatory T (Treg) cells causes lethal, CD4+ T cell-driven autoimmune diseases in scurfy (SF) mice and humans." (PMID 29270168, 2017). "Previous studies demonstrated mucosal antigen administration results in expansion of Foxp3+ and LAP+ regulatory T cells (Tregs), suggesting oral delivery of self-antigens might represent an effective means for modulating autoimmune disease." (PMID 28205558, 2017). "Mice with Treg cell-specific deletion of Lkb1 develop a fatal early-onset autoimmune disease, with no Foxp3 expression in most Treg cells." (PMID 28621313, 2017). "CD4+FOXP3+ regulatory T cells (Tregs) are a subset of CD4 T cells that play an essential role in maintaining peripheral immune tolerance, controlling acute and chronic inflammation, allergy, autoimmune diseases, and anti-cancer immune responses." (PMID 26623425, 2015). "In line with our findings, other groups have also reported that effector cytokine secretion is mainly limited to the FoxP3+Helios− T cell subset, while FoxP3+Helios+ Tregs are non-cytokine producers, both in healthy and autoimmune disease settings." (PMID 26343373, 2015). "Considering that the balance between Th17 and regulatory T cells is critical in autoimmune diseases and that a high frequency of regulatory T cells migrate to the CNS during EAE recovery, we analyzed the frequency of Foxp3+ regulatory T cells in the spleen and at the site of inflammation." (PMID 24401094, 2014). "In this study, we explore if adoptive transfer of Foxp3+ iTreg cells, specific for the same antigen and generated in vitro by stimulation of naive CD4+ Tconv cells in the presence of IL-2 and TGF-β1, can equally offer protection from CNS autoimmune disease." (PMID 25238105, 2014). "CD4+CD25+Foxp3+ Tregs account for 5%-10% of the CD4+ T cell panel in healthy human and mice, which are sufficient to play an important role in the maintenance of immune homeostasis and the limitation of autoimmune disease." (PMID 25475342, 2014). "A lack of FoxP3-expressing T-cells can lead to autoimmune disease, whereas an abundance of FoxP3-expressing regulatory T-cells can result in immune deficiency." (PMID 23537231, 2013). "IL-10--producing B cells, Foxp3-expressing T cells (Tregs) and the IDO-expressing dendritic cells (pDC) are able to modulate inflammatory processes, to induce immunological tolerance and, in turn, to inhibit the pathogenesis of autoimmune disease." (PMID 23800367, 2013).
autoimmune disease (continued). "Although Th2 cells and FoxP3+ Tregs have been reported to be critical for maintaining immune tolerance in autoimmune diseases, no significant increase of IL-4-producing or FoxP3 expression CD4+ cells was found in MOG35-55/I-Ab dimer-treated mice." (PMID 23077616, 2012). "In recent studies on fields of inflammatory diseases, including cancer and autoimmune diseases, the AhR has been reported to act as an important molecule that regulates the differentiation of Tregs, which express CD25 and the transcription factor, forkhead box P3 (Foxp3)." (PMID 38542428, 2024). "This article described the unique role of Treg cells in autoimmune diseases, which exhibited their inhibition function in vitro in a contact-dependent manner and preferentially expressed high levels of CD25, forkhead, and winged-helix family transcription factor forkhead box P3 (FOXP3) (Tregs)." (PMID 36248874, 2022). "As Foxp3− Th cells expressing both NRP1 and PD‐1 were associated with autoimmune disease, we next tested whether or not NRP1/PD‐1‐expressing conventional Th cells were directly pathogenic." (PMID 36069030, 2022). "FOXP3, RORγt, STAT3, RelA/p65 (NF-κB), and c-Fos/c-Jun (AP-1) are transcription factors targeted by SIRT1, which are well-studied and are crucial to a balanced immune system, but the role of SIRT1 in autoimmune disease is only in the incipient stage, especially in the progression of SLE." (PMID 33981300, 2021). "The question now arises as to whether a HSD could influence the instability of forkhead box P3 (FOXP3) cells in the lamina propria, as it has been found that there is a reciprocal relationship between TH17 cells and TREG cells in the gut of autoimmune disease models." (PMID 32696457, 2020). "The abnormal expression of Foxp3 could result in IRF4 missing, resulting in unable to start the transcription of downstream gene and compromise the immunosuppressive function of Treg cells in patients with autoimmune diseases." (PMID 31380412, 2019). "Abnormal methylation changes of Foxp3 have been reported with several autoimmune diseases, which could also not be confirmed in our EAU model." (PMID 30254507, 2018). "Unlike CD4+CD25+Foxp3+ Tregs, which dominate hematological system tumors and autoimmune diseases, γδ T cells play a key role in the pathological progress of AMI and it may be associated with the IL-17A mediated pathway, but the specific mechanism is unknown." (PMID 29976209, 2018). "However, to the best of our knowledge, the DNA methylation dynamics of Tbx21, Gata3, Rorc, and Foxp3 during the development of autoimmune disease has not yet been studied and was therefore the subject of our study, whereby we chose uveitis as a disease model." (PMID 30254507, 2018). "Foxp3, a transcription factor mainly expressed in CD25+CD4+ regulatory T cells (Tregs), plays a major role in maintaining homeostasis in immune regulation by inhibiting the proliferation of effector T cells, thereby maintaining tolerance and preventing development of autoimmune diseases." (PMID 22323550, 2012). "Recently however, some papers have shown correlation of high expression of FoxP3 and low or no expression of IL-7R alpha CD127low/- on the cell surface Humans without functional FoxP3 protein have an autoimmune disorder called IPEX with auto-antibodies against a diversity of organs." (PMID 17206281, 2007). "In addition, when FoxP3 was removed as could be done in model systems either by gene knockout approach or a conditional deletion by diphtheria toxin in transgenic FoxP3-DTR mice, multiple inflammatory and autoimmune diseases resulted." (PMID 37671156, 2023). "MRG-001 given at the mid-dose dramatically increased circulating CD4+Foxp3+ and CD8+Foxp3+ Tregs suggesting its immunomodulatory properties and that MRG-001 could be used as an immunoregulatory therapy in a variety of human diseases including autoimmune diseases and transplant rejection." (PMID 37633275, 2023).